LAMB3 (laminin subunit beta 3)
Diseases named in the same sentence as LAMB3 in open-access papers (continued):
Sharing a sentence is not in itself a finding about the gene and the disease.
thyroid cancer (8 papers, 2018 to 2024). "LAMB3 was reported to be up-regulated in thyroid cancer and promote papillary thyroid cancer cell migration and invasion by activating the c-MET/AKT signaling pathway." (PMID 36612197, 2022). "We first evaluated LAMB3 expression in normal and tumor tissues derived from the same thyroid cancer patients." (PMID 29426928, 2018). "In our data evaluating the LAMB3 expression pattern in the human thyroid cancer tissues, all the tumor tissues had higher LAMB3 expression compared to normal tissues." (PMID 29426928, 2018). "However, our study have strength in that to our best of knowledge, we evaluated for the first time the expression of LAMB3 in the thyroid carcinoma." (PMID 29426928, 2018). "Therefore, we hypothesized that LAMB3 overexpression is a common finding in thyroid cancer and might be important for the aggressive features, such as metastasis, of PTC." (PMID 29426928, 2018). "In thyroid cancer and head and neck squamous cell carcinoma (HNSCC), LAMB3 is significantly upregulated and promotes proliferation and metastasis." (PMID 32039003, 2019). "While LAMB3 is involved in the invasive and metastatic abilities of several tumor types, including those found in the colon, pancreas, lung, cervix, stomach, and prostate, its mechanism of action in thyroid cancer has not been investigated previously." (PMID 29426928, 2018). "However, the molecular role of LAMB3 in thyroid cancer has not yet been fully elucidated." (PMID 29426928, 2018).
gastric cancer (7 papers, 2012 to 2024). A primary or metastatic malignant neoplasm involving the stomach. "In gastric cancer, the up-regulation of LAMB3 plays an important role in cancer progression." (PMID 36612197, 2022). "LAMB3 has also been reported to be hypomethylated and upregulated in gastric cancer." (PMID 25079072, 2014). "In addition, a study on gastric cancer has suggested LAMB3 and LAMC2 chains accumulate intracellularly and are related with cancer progression, while epigenetic silencing of the LAMA3 chain may lead to an inability of synthesizing the basement membrane, which may affect cancer cell invasion." (PMID 31182680, 2019).
head and neck squamous cell carcinoma (6 papers, 2019 to 2024). A squamous cell carcinoma that arises from any of the following anatomic sites: lip and oral cavity, nasal cavity, paranasal sinuses, pharynx, larynx, and salivary glands. "Recently, a study showed that siRNA-mediated silencing of LAMB3 could enhance the sensitivity of head and neck squamous cell carcinoma cells to cisplatin, which may explain why PIGR can also increase the sensitivity of CRC cells to cisplatin." (PMID 35992840, 2022). "This is supported by head and neck squamous cell carcinoma (HNSCC) study, where direct regulation of LAMB3 by miR-218 has been described and targeting of LAMB3 by miR-218 resulted in significant inhibition of cell migration and invasion." (PMID 35008952, 2022). "In terms of partial epithelial-mesenchymal transition (p-EMT), MYOSLID expression in head and neck squamous cell carcinoma (HNSCC) was closely correlated with Slug, PDPN, and LAMB3, and is a key regulator of tumor cell survival." (PMID 34257164, 2021).
pancreatic adenocarcinoma (6 papers, 2018 to 2024). "LAMB3 is involved in invasive and metastatic behaviors of various cancers, especially pancreatic adenocarcinoma (PAAD) by modulating the PI3K (phosphoinositide 3-kinases)/ Akt signaling pathway." (PMID 38114514, 2023). "Amongst, increased expressions of LAMB3 and ITGB6 were significantly associated with poor prognosis of patients with pancreatic adenocarcinoma in this study, underlying the importance of the identified enriched pathways in PDAC." (PMID 33194391, 2020). "Over-expression of LAMB3 is correlated to clinicopathologic features and reduced survival in pancreatic adenocarcinoma patients." (PMID 30519576, 2018). "Other researchers found that a combined signature of high LAMA3, LAMB3, and LAMC2 expression was a stronger predictor of poor prognosis in pancreatic adenocarcinoma than individual genes." (PMID 39218967, 2024). "We used Gene Expression Omnibus (GEO) database and identified six genes (COL1A2, ITGA2, ITGB6, LAMA3, LAMB3, and LAMC2) that could affect the survival rate of pancreatic adenocarcinoma patients." (PMID 35899199, 2022).
papillary thyroid cancer (5 papers, 2018 to 2025). "Studies have shown that LAMB3 leads to tumor invasion via Akt activation induced by the HGF/c-MET axis in papillary thyroid cancer." (PMID 31485443, 2019). "Our findings reveal a novel mechanism of action for LAMB3 in papillary thyroid cancer cells." (PMID 29426928, 2018).
squamous cell carcinoma (5 papers, 2012 to 2025). A carcinoma arising from squamous epithelial cells. "Tumor epithelial clusters expressed canonical squamous carcinoma markers such as CLDN1, LAMB3, TP63, CDKN2A, EPCAM, and SERPINB2, validating their malignant identity, while stromal and immune subsets displayed expected transcriptional programs." (PMID 41510303, 2025). "In non-responders with squamous cell carcinoma, LAMB3, ITGB8, and WNT5A genes were highly expressed." (PMID 35135489, 2022). "Consistent with these previous studies, our analysis of LAMB3 and LAMB4 from the TCGA-HNSC dataset indicated that both LAMB3 and LAMB4 could serve as prognostic markers for squamous cell carcinoma." (PMID 36081907, 2022).
colon carcinoma (4 papers, 2022 to 2023). "The expression levels of LAMB3 and ERO1A were assessed by IHC in tissue array 1, which includes 90 rectal cancer samples, and tissue array 3, which includes 30 colon cancer samples." (PMID 36209225, 2022).
melanoma (4 papers, 2015 to 2025). A malignant, usually aggressive tumor composed of atypical, neoplastic melanocytes. "LAMB3, in particular, has been implicated in melanoma metastasis, aligning with our cross-cancer comparative findings." (PMID 40604111, 2025). "These experiments demonstrate that DNA methylation of the non-CG island P2 promoter of IGF1 can directly silence gene expression, as previously shown when plasmid constructs containing the non-CG island promoters of LAMB3 and RUNX3 genes were transfected into HaCaT cells and 623 melanoma cells." (PMID 25789079, 2015).
lung adenocarcinoma (3 papers, 2019 to 2024). A carcinoma that arises from the lung and is characterized by the presence of malignant glandular epithelial cells. "The LAMB3 protein is a major component of the extracellular matrix and basal membrane and promotes cell migration and tumorigenicity in SCID mice and lung adenocarcinoma." (PMID 39408909, 2024).
ovarian carcinoma (3 papers, 2022 to 2024). A malignant neoplasm originating from the surface ovarian epithelium. "Another study found LAMB3 mRNA expression to be greater in endometrial cancer than in ovarian cancer." (PMID 39408909, 2024). "Overexpression of LAMB3 was also observed in platinum-resistant ovarian cancer patients, suggesting this gene’s role in drug resistance." (PMID 35008952, 2022). "The expression of both LAMB3 mRNA and protein has been reported to be greater in ovarian cancer than in normal ovarian tissue, based on studies that examined correlations between laminin expression and prognosis in ovarian cancer using several open sources including cBioPortal and ONCOMINE." (PMID 39408909, 2024). "It is interesting to note that when ovarian cancer cells are detached from the ECM, upregulation of both PCMT1 and LAMB3 and spheroid formation are observed." (PMID 35033172, 2022). "Interestingly, PCMT1 was released from ovarian cancer cells, and interacted with the ECM protein LAMB3, which binds to integrin and activates FAK-Src signaling to promote cancer progression." (PMID 35033172, 2022). "In this study, we evaluated the clinical relevance of PCMT1 levels with ovarian cancer progression in patient samples and dissected the mechanism of how extracellular PCMT1 contributes to cancer progression through modulation of LAMB3, which may be used as a serum marker for monitoring metastasis." (PMID 35033172, 2022).
cervical squamous cell carcinoma (2 papers, 2017 to 2022). A squamous cell carcinoma arising from the cervical epithelium. "In addition, ITGA2 has also been demonstrated to promote PDAC progression via the focal adhesion pathway, and LAMB3 is also identified as an oncogene related to the focal adhesion pathway in cervical squamous cell carcinoma." (PMID 36612197, 2022).
enamel hypoplasia (2 papers, 2023 to 2025). "Individuals with EB caused by mutations in laminin-332 (Lama3, Lamb3, Lamc2), α6ß4-integrin (TGB4, ITGA6) gene and type XVII collagen (Col17A1) are associated with enamel hypoplasia." (PMID 37511997, 2023).
toxoplasmosis (2 papers, 2020 to 2025). A parasitic disease contracted by the ingestion or fetal transmission of toxoplasma gondii. "Moreover, based on the 51 common supertargets of the cohort and personalized approach the down-regulated genes HLA-DRA and HLA-DRB1 were found to be prominently involved in all seven highlighted pathways, while the up-regulated gene LAMB3 played an additional role in toxoplasmosis." (PMID 33273683, 2020).
amelogenesis imperfecta (1 paper, 2021). Amelogenesis imperfecta (AI) represents a group of developmental conditions affecting the structure and clinical appearance of the enamel of all or nearly all the teeth in a more or less equal manner, and which may be associated with morphologic or biochemical changes elsewhere in the body. "Mutations in AMELX, DLX3, LAMA3, LAMB3, and WDR72 were reported in both non-syndromic and syndromic amelogenesis imperfecta." (PMID 33672174, 2021).
chronic pancreatitis (1 paper, 2023). A chronic inflammatory process causing damage and fibrosis of the pancreatic parenchyma. "Other observations included a less robust correlation between LAMA3 with pathological stages (p = 0.04) and LAMB3 with male patients (p = 0.02) and with chronic pancreatitis history (p = 0.03)." (PMID 37779898, 2023).
dentinogenesis imperfecta (1 paper, 2022). Dentinogenesis imperfecta (DGI) is a hereditary dentin defect characterized by abnormal dentin structure resulting in abnormal tooth development. "Many types of OI are characterized by dentinogenesis imperfecta, and a defect in the LAMB3 gene may underlie the molecular pathogenesis of this condition." (PMID 36289625, 2022).
dermatitis (1 paper, 2018). An inflammatory process affecting the skin. "Laminin subunit beta 3 (LAMB3) and hydroxysteroid 11-beta dehydrogenase 1 (HSD11B1) genes, which influence hair morphogenesis and dermatitis in both mice and humans, respectively, were identified as the most likely candidates for influencing mature fleece weight within the associated QTL." (PMID 29670642, 2018).
diffuse large B-cell lymphoma (1 paper, 2020). "Finally, certain lymphoproliferative diseases are also associated with expression of COL6A1, COL18A1, MMP3 and TIMP1, and a subset of patients with diffuse large B cell lymphoma and adverse prognosis show decreased expression of POSTN, SPARC, COL1A1, COL3A1,CSTK, MMP9 and LAMB3." (PMID 33379263, 2020).
esophageal squamous cell carcinoma (1 paper, 2014). Esophageal squamous cell carcinoma (ESCC) is a type of esophageal carcinoma (EC) that can affect any part of the esophagus, but is usually located in the upper or middle third. "LAMB3 expression is higher in malignant esophageal squamous cell carcinoma than in normal tissue, and expression correlates with depth of invasion and survival." (PMID 25079072, 2014).
gastric tumor (1 paper, 2020). "Early in 2011, hypomethylation induced by abnormal overexpression of LAMB3 contributes to gastric tumor procession." (PMID 32528944, 2020).
hepatocellular carcinoma (1 paper, 2019). A malignant tumor that arises from hepatocytes. "Despite its oncogenic role, LAMB3 can also act as a tumor suppressor gene in hepatocellular carcinoma progression." (PMID 32039003, 2019).
nasal polyps (1 paper, 2023). "LAMB3 is involved in the regulation of cell adhesion and migration, and its upregulation may contribute to the abnormal growth and invasion of nasal polyps in ECRSwNP." (PMID 37867480, 2023).
nasopharyngeal carcinoma (1 paper, 2024). A carcinoma arising from the nasopharyngeal epithelium. "It was shown that the knockdown of LAMB3 in nasopharyngeal carcinoma decreased radioresistance, which is not in line with our finding of its reduced expression in DU145 RR cells, but it completely fits to our functional studies." (PMID 39149513, 2024).
respiratory infection (1 paper, 2023). "The most significantly increased ECM protein was laminin beta 3 (LAMB3), which has been shown to be used as a receptor for Pseudomonas aeruginosa during respiratory infection." (PMID 37566063, 2023).
thyroid (1 paper, 2024). "In our study, mechanistic exploration revealed that LAMB3 was a LINC02454-coexpressed gene related to the ECM-receptor interaction pathway in thyroid carcinogenesis." (PMID 39218967, 2024).
tongue cancer (1 paper, 2015). A malignant neoplasm affecting the tongue. "After comparison between tongue cancer and corresponding normal samples, GNA15, PPP2R3A, LAMB3, HSPA2, and MAP4K3 were identified as five top-ranking genes." (PMID 26336805, 2015).
triple-negative breast carcinoma (1 paper, 2025). An invasive breast carcinoma which is negative for expression of estrogen receptor (ER), progesterone receptor (PR), and human epidermal growth factor receptor 2 (HER2). "Melatonin inhibits the infiltration of triple-negative breast cancer-associated fibroblasts (CAFs) by downregulating the expression of laminin beta-3 (LAMB3) and the C-X-C chemokine ligand 2 (CXCL2)." (PMID 40756978, 2025).
viral infection (1 paper, 2025). "The E6 oncogenic protein of HR HPV‐16 reduced hsa‐miR‐218 expression and in the transcriptional level increases LAMB3 expression, may promote viral infection and tumorigenesis." (PMID 39185567, 2025).
vitiligo (1 paper, 2024). Generalized well circumscribed patches of leukoderma that are generally distributed over symmetric body locations and is due to autoimmune destruction of melanocytes. "Therefore, LAMB3 and laminin-332 potentially act as driving regulators and predictive biomarkers for melanocyte growth and vitiligo progression." (PMID 38200141, 2024). "Autologous serum- and feeder-free cultured epithelium showcases comparable efficacy, increased safety over serum- and feeder-dependent epithelium, revealing the role of LAMB3+ keratinocytes and ZNF90+ fibroblasts in vitiligo." (PMID 38200141, 2024). "From bench to bedside and back again, we found that, in the absence of serum and feeder, LAMB3+ basal keratinocytes and ZNF90+ fibroblasts may promote repigmentation in cultured autologous epithelial sheets in the treatment of patients with refractory vitiligo." (PMID 38200141, 2024).
cancer (75 papers, 2008 to 2025). A tumor composed of atypical neoplastic, often pleomorphic cells that invade other tissues. "Several studies reported that LAMB3 overexpression is linked to cancer hallmarks, including cell proliferation, migration, invasion, and cancer progression via the PI3K/Akt signaling pathway, AKT-FOXO3/4, and c-MET/Akt signals." (PMID 38473784, 2024). "In outline, the prognosis of cancer patients can be influenced by LAMB3 expression, which is closely linked to the immune infiltration of tumor cells." (PMID 37577750, 2023). "It has been demonstrated that LAMB3 plays a significant role in the progression of some types of cancer, and its function is closely associated with attachment, migration, and interaction with other components of the extracellular matrix." (PMID 37577750, 2023). "Third, despite our findings that immune cell infiltration and associated immune targets in human cancers are closely linked to LAMB3 gene expression, we lack direct evidence that LAMB3 influences prognosis by participating in immune infiltration." (PMID 37577750, 2023). "In 17 cancers, the mRNA for LAMB3 is expressed differently and has good diagnostic and prognostic value in 22 cancers." (PMID 37577750, 2023). "Meanwhile, in the constructed forest plot of LAMB3 and clinicopathological features, high LAMB3 expression in most cancers, including LUSCLUAD, KIRP, KIRC, and HNSC, is associated with a poor prognosis." (PMID 37577750, 2023). "In conclusion, our pan-cancer analysis revealed that LAMB3 is an independent risk factor for multiple cancers and is closely linked to their development and prognosis." (PMID 37577750, 2023). "LAMB3 was found to be implicated in the pathway in cancer and the PI3K-AKT signaling pathway." (PMID 38473784, 2024). "The ROC curve was used to evaluate the diagnostic value of LAMB3 in pan-cancer." (PMID 37577750, 2023). "In addition to confirming that LAMB3 expression is closely linked to the biological processes of immune cells and immune-related molecules in the majority of cancers, our research provides additional insight into the broader suitability of LAMB3 for tumors." (PMID 37577750, 2023). "Cox regression and Nomogram analysis show that LAMB3 is an independent risk factor for 15 cancers." (PMID 37577750, 2023). "The results indicate that LAMB3 has excellent diagnostic value in most cancers." (PMID 37577750, 2023). "Significant differences in LAMB3 expression were observed in cancer tissues compared with paracancerous tissues." (PMID 41139196, 2025). "The LAMB3 gene was selected for further functional analysis due to its involvement in pathways in cancer and the PI3K-Akt signaling pathway." (PMID 38473784, 2024). "The involvement of LAMB3 in proliferation, migration, invasion and other cancer properties requires additional investigation." (PMID 38473784, 2024). "Based on these data, LAMB3 appears to be a potential therapeutic drug target and prognosis of cancer progression." (PMID 38473784, 2024). "In S-phase tissues, the expression of LAMB3 and HIF1A, associated with pathways in cancer, increased in EMS patients, while the expression of PAM, related to responses to hypoxia, was reduced." (PMID 39408909, 2024). "Stress-like cancer cells have higher tumor-seeding capabilities, and LAMB3, as a key gene in stress-like tumor cells, has been reported to encode one of the heterotrimeric glycoproteins of laminin-5 (LN5), which promotes tumor invasion and metastasis." (PMID 37138324, 2023). "As a result, LAMB3 has the potential to be a novel pan-cancer biomarker, a potential therapeutic target, and a player in tumor formation and progression." (PMID 37577750, 2023). "Immune cell infiltration levels were significantly correlated with LAMB3 expression in most types of cancer." (PMID 37577750, 2023).